CYP4F12 (cytochrome P450 family 4 subfamily F member 12)
Description:
A cytochrome P450 monooxygenase involved in the metabolism of endogenous polyunsaturated fatty acids (PUFAs). Mechanistically, uses molecular oxygen inserting one oxygen atom into a substrate, and reducing the second into a water molecule, with two electrons provided by NADPH via cytochrome P450 reductase (CPR; NADPH-ferrihemoprotein reductase). Catalyzes the hydroxylation of carbon hydrogen bonds, with preference for omega-2 position. Metabolizes (5Z,8Z,11Z,14Z)- eicosatetraenoic acid (arachidonate) toward 18-hydroxy arachidonate. Catalyzes the epoxidation of double bonds of PUFAs such as docosapentaenoic and docosahexaenoic acids. Has low omega-hydroxylase activity toward leukotriene B4 and arachidonate. Involved in the metabolism of xenobiotics. Catalyzes the hydroxylation of the antihistamine drug ebastine.
Synonyms: CYPIVF12; F22329_1
Tractability: Small molecule: it belongs to a druggable protein family. Antibody: UniProt predicts a signal peptide or a membrane-spanning region. PROTAC: ubiquitination databases record sites on it; its protein half-life has been measured; a small molecule that binds it is known.
Target class: Cytochrome P450; Enzyme; Cytochrome P450 family 4F; Cytochrome P450 family 4
Gene: Protein-coding gene on chromosome 19 (15,673,018 to 15,698,817, forward strand). Ensembl gene ENSG00000186204.
Subcellular location: Endoplasmic reticulum membrane; Microsome membrane
Pathways (Reactome):
Metabolism: Eicosanoids; Fatty acids
Gene Ontology:
Molecular function: oxidoreductase activity, acting on paired donors, with incorporation or reduction of molecular oxygen, reduced flavin or flavoprotein as one donor, and incorporation of one atom of oxygen; protein binding; alkane 1-monooxygenase activity; arachidonate epoxygenase activity; leukotriene-B4 20-monooxygenase activity; monooxygenase activity; heme binding; iron ion binding; oxidoreductase activity, acting on paired donors, with incorporation or reduction of molecular oxygen
Biological process: arachidonate metabolic process; epoxygenase P450 pathway; fatty acid metabolic process; leukotriene B4 catabolic process; long-chain fatty acid metabolic process; menaquinone catabolic process; phylloquinone catabolic process; pressure natriuresis; renal water homeostasis; sodium ion homeostasis; very long-chain fatty acid metabolic process; vitamin E metabolic process; xenobiotic metabolic process
Cellular component: apical plasma membrane; cytoplasm; endoplasmic reticulum membrane; intracellular membrane-bounded organelle
Genetic constraint (gnomAD): Loss-of-function variants: 61 observed, 57.85 expected, observed/expected ratio (o/e) 1.05, 90% interval 0.86 to 1.3. The upper end of that interval is the gene's LOEUF score, 1.3, which puts it in group 5 of 6, group 1 being the genes least tolerant of losing a copy. Missense variants: 711 observed, 705.15 expected, observed/expected ratio (o/e) 1.01, 90% interval 0.95 to 1.07. Synonymous variants: 263 observed, 275.81 expected, observed/expected ratio (o/e) 0.95, 90% interval 0.86 to 1.06.
Homologues: Orthologues: chimpanzee CYP4F12 (97% identical), rat Cyp4a1 (43% identical), mouse Cyp4a32 (43% identical), mouse Cyp4a10 (42% identical), rat Cyp4a3 (42% identical), tropical clawed frog cyp4b1.5 (41% identical), mouse Cyp4a31 (41% identical), tropical clawed frog cyp4b1.2 (41% identical), tropical clawed frog XB5810926 (40% identical), mouse Cyp4a30b (39% identical), zebrafish cyp4t8 (36% identical), zebrafish cyp4f3 (32% identical), and 29 more. Paralogues in human: CYP4F11 (83% identical), CYP4F2 (81% identical), CYP4F3 (78% identical), CYP4F8 (77% identical), CYP4F22 (62% identical), CYP4A11 (43% identical), CYP4A22 (42% identical), CYP4B1 (41% identical), CYP4X1 (40% identical), CYP4Z1 (36% identical), CYP4V2 (32% identical), CYP19A1 (22% identical).
Diseases named in the same sentence as CYP4F12 in open-access papers:
CYP4F12 is named in the same sentence as 41 diseases in open-access papers, as found by Europe PMC text mining. Sharing a sentence is not in itself a finding about the gene and the disease. The quoted sentences say what the papers report.
glioma (4 papers, 2016 to 2025). A benign or malignant brain and spinal cord tumor that arises from glial cells (astrocytes, oligodendrocytes, ependymal cells). "In the combined analysis of all PAVs the strongest association for risk of glioma was provided by rs593818 responsible for the XM_006722850.1(CYP4F12):c.1117A>G, p.(Ser373Gly) amino acid change (P=1.24 × 10−5), albeit non-significant on a genome-wide basis." (PMID 26264438, 2016). "Genetic variants in CYP4F12 were associated with glioma susceptibility." (PMID 37237274, 2023).
cervical cancer (3 papers, 2023 to 2025). A primary or metastatic malignant neoplasm involving the cervix. "Significant associations of CYP4F12 included favorable prognosis in cervical cancer; in esophageal cancer, they were associated with reduced migration and immune modulation; and in ovarian mucinous tumors, they were associated with responsiveness to oxidative stress." (PMID 40723371, 2025). "CYP4F12 encodes cytochrome p450 4F12 and an intron retention event in the CYP4F12 gene, has been previously demonstrated to hold prognostic value in cervical cancer, being incorporated into a retained intron-based signature model to predict overall survival in patients with cervical cancer." (PMID 37924098, 2023). "In addition, CYP4F12 was proved as an indicator in the prognosis and immune infiltration of cervical cancer." (PMID 37237274, 2023).
bladder cancer (2 papers, 2021 to 2025). "Indeed, deregulation of some CYP proteins has been proposed as a risk factor for the development of bladder cancer, but little is known about the role of CYP4F12, in particular, in bladder cancer progression." (PMID 33797847, 2021).
hepatocellular carcinoma (2 papers, 2019 to 2021). A malignant tumor that arises from hepatocytes. "Evaluation of the CYP4 expression profile in hepatocellular carcinoma (HCC) showed that CYP4F2, CYP4F12, and CYP4V2 mRNA levels were negatively correlated with cell-cycle-associated genes, suggesting that these CYP4 genes are favorable prognostic factors in HCC." (PMID 31480463, 2019).
bladder urothelial carcinoma (1 paper, 2025). "CYP4B1 and CYP4F12 display low expression in normal bladder tissue and are detectable in certain cases of bladder urothelial carcinoma (BLCA), as reported by the Human Protein Atlas." (PMID 40723371, 2025).
breast carcinoma (1 paper, 2025). "On the other hand, breast cancer patients (n = 1100) with low CYP4B1 and CYP4F12 expression levels showed better cumulative survival, whereas patients with high CYP4F3 expression had better overall survival than their counterparts." (PMID 40723371, 2025). "The CYP4B1, CYP4F12, and CYP4F3 overall survival (OS) analyses were retrieved using the TIMER2.0 web server in breast cancer." (PMID 40723371, 2025). "Bioinformatics indicated that breast cancer is influenced by genes like CYP4B1, CYP4F12, and CYP4F3." (PMID 40723371, 2025). "This study emphasizes CYP4B1, CYP4F12, and CYP4F3 gene expression levels, presenting tumor versus normal tissue analysis, their expression adjusted by stages, their correlation with BRCA1, BRCA2, and ESR1, the estrogen receptor status, and the overall survival analysis in breast cancer patients." (PMID 40723371, 2025).
colon tumour (1 paper, 2023). "The same retained intron event identified in our study has also been found to be negatively regulated in both left- and right-sided colon tumour tissues compared to normal tissues, suggesting a wider impact of CYP4F12 dysregulation on cancer pathogenesis." (PMID 37924098, 2023).
esophageal cancer (1 paper, 2025). A primary or metastatic malignant neoplasm involving the esophagus. "A study identified CYP4F12 as a histone acetylation–responsive gene in esophageal cancer, showing increased expression following trichostatin A treatment through the p300-mediated acetylation of H3K18 and H3K27." (PMID 40723371, 2025).
gastric cancer (1 paper, 2025). A primary or metastatic malignant neoplasm involving the stomach. "Likewise, CYP4F12 exhibited low to undetectable expression in both normal gastric tissue and gastric cancer." (PMID 40723371, 2025). "Consequently, based on the evidence, CYP4F12 did not appear to serve as a relevant biomarker or therapeutic target in gastric cancer." (PMID 40723371, 2025).
liver cancer (1 paper, 2021). An epithelial or non-epithelial malignant neoplasm that arises from the liver. "Expression of CYP4F12 is positively correlated with low clinical stages and is a prognostic biomarker for overall survival in liver cancer." (PMID 33450964, 2021).
prostate carcinoma (1 paper, 2025). A carcinoma that arises from epithelial cells of the prostate gland. "To date, no studies have specifically investigated the expression or functional role of CYP4F12 in prostate cancer." (PMID 40723371, 2025). "While polymorphisms in cytochrome P450 family genes were examined concerning prostate cancer, no direct association between CYP4F12 and disease progression or treatment response was established." (PMID 40723371, 2025).
steatosis (1 paper, 2024). Increased lipid within the cytoplasm of cells. "In human patients, the CYP4F12, CYP4F22, and CYP4V2 mRNA levels increase in steatosis and MASH, while the levels of CYP4B1, CYP4X1, and CYPZ1 mRNAs decrease in steatosis and MASH while the mRNA for these genes increases in HCC." (PMID 40452921, 2024).
uterine cancer (1 paper, 2025). Primary or metastatic malignant neoplasm involving the uterine corpus and/or the cervix. "Although direct evidence linking CYP4F12 to uterine cancer is missing, data from the Human Protein Atlas showed its expression across multiple malignancies, including uterine and liver cancers, with higher levels observed in hepatic tumors." (PMID 40723371, 2025). "In uterine cancer, CYP4F12 was identified as a favorable prognostic marker, suggesting that elevated expression may be associated with improved clinical outcomes." (PMID 40723371, 2025).
tumor (8 papers, 2018 to 2025). "Transcriptomic data from TCGA and GSE53624 confirmed its overexpression in tumor tissue and associated high CYP4F12 levels with a favorable prognosis." (PMID 40723371, 2025). "Since overexpression of CYP4F12 is involved in inhibition of tumor progression and metastasis and its low expression has been associated with poor patient survival; increased expression of CYP4F12 in the combination therapy demonstrates its therapeutic advantage." (PMID 38992681, 2024). "Then we calculated the enrichment fractions of CYP4F12 and key pathways of tumor development to obtain the correlation between genes and pathways." (PMID 37414830, 2023). "In this study, we examed the expression of CYP4F12 in a variety of tumor types, explored its latent role in HNSC immune infiltration, and evaluated its prognostic value in HNSC patients." (PMID 37414830, 2023). "The results showed that CYP4F12 was low expressed in tumor tissues, participated in a variety of phenotypic changes of HNSC and affected immune cell infiltration." (PMID 37414830, 2023). "With the increase of tumor grade, the infiltration and spreading rate of cancer cells increased, and the expression of CYP4F12 should be gradually decreased, but there is an abnormally high expression in grade 4 tumor cells." (PMID 37414830, 2023). "We then determined the expression of CYP4F12 in various cultured tumor cells based on the RNA-SEQ data obtained from the CCLE database." (PMID 37414830, 2023). "In particular, with regard to tumor grading, we found that CYP4F12 expression gradually decreased in grades 1–3 and reached the highest in grade 4." (PMID 37414830, 2023). "We then verified the expression of CYP4F12 in the GEO database and patient specimens collected by our laboratory, the results also showed that CYP4F12 was low expressed in tumor tissues." (PMID 37414830, 2023). "The result showed that CYP4F12 is expressed in all tumor cell lines, but generally at low levels." (PMID 37414830, 2023). "Since CYP4F12 has been shown to inhibit tumor cell migration in vitro, we hypothesized that CYP4F12 may be a promising HNSC biomarker that could predict anticancer therapy efficacy and patient prognosis." (PMID 37414830, 2023). "In addition, the expression of CYP4F12 gradually decreased with the increase of tumor grade from grade 1 to grade 3, while peaked at grade 4." (PMID 37414830, 2023). "In addition, we found that the gene with hazard ratio < 1 (CYP4F12) show a lower protein level in tumor tissues." (PMID 37237274, 2023). "CYP4F12 expression was also correlated with tumor stage (TNM staging)." (PMID 36360213, 2022). "Pathway analysis indicated that CYP4F12 may play a key role in tumor cell migration and apoptosis." (PMID 37414830, 2023). "This is indicative that CYP4F12 may be involved in tumor progression and drug response." (PMID 36360213, 2022). "CYP4B1, CYP4F12, and CYP4F3 gene expression levels were found to correlate with ESR1; then, a tumor versus normal tissue analysis and an overall survival evaluation in several types of cancer were conducted." (PMID 40723371, 2025). "The HOXA4, CYP4F12, and ADM2 were positively correlated with the immune and stromal score but negatively correlated with tumor purity." (PMID 37955724, 2023).
tumor (continued). "The results indicated that the expression levels of (A) CYP4B1 and (B) CYP4F12 genes were higher (p < 0.05) in normal tissue than in tumor tissue, whereas (C) CYP4F3 expression levels were not significantly different." (PMID 40723371, 2025). "These genes include three tumour suppressors (DMBT1, MTUS1, and KLRC1), two genes involved with cell communication and myelin (GJB1 and KLK6), and a P450 monooxygenase involved in the synthesis of cholesterol and lipids (CYP4F12)." (PMID 37628980, 2023). "First, given the complex interactions between tumors and the microenvironment, we have not demonstrated in vivo that CYP4F12 has tumor suppressive effects." (PMID 37414830, 2023). "However, there was no significant change in CYP4F12 expression level among different tumor stages or lymph node metastasis status." (PMID 37414830, 2023). "Therefore, CYP4F12 can regulate cell migration by directly affecting the EMT process in HNSC, and may also affect tumor cell migration by influencing the tumor microenvironment." (PMID 37414830, 2023).
cancer (4 papers, 2023 to 2025). A tumor composed of atypical neoplastic, often pleomorphic cells that invade other tissues. "To clarify the importance of CYP4F12 expression in tumors, we first analyzed CYP4F12 expression in a variety of cancers using TIMER." (PMID 37414830, 2023). "The study provides a comprehensive approach to the expression, clinical relevance, and genetic variation of the CYP4B1, CYP4F12, and CYP4F3 genes in breast and other cancers." (PMID 40723371, 2025). "The CYP4B1, CYP4F12, and CYP4F3 overall survival (OS) analyses were conducted using the TIMER2.0 in pan-cancer." (PMID 40723371, 2025). "However, survival analyses indicate that CYP4F12 does not serve as a significant prognostic marker in this cancer type." (PMID 40723371, 2025).
colon (1 paper, 2020). "Our results indicate a suppression of enzymes involved in various stages of carcinogen breakdown including CYP2C8, CYP4F12, GSTA1, and UGT1A within right colon tumors." (PMID 32293332, 2020).
infection (1 paper, 2023). The state of being infected such as from the introduction of a foreign agent such as serum, vaccine, antigenic substance or organism. "The age of CYP4F12 high-expression group was lower than that of the low-expression group, the infection rate of HPV in the high-expression group was significantly higher than that in low-expression group, and the perineural invasion was also less frequent." (PMID 37414830, 2023).
CYP4F12 also shares sentences with these, for which no sentence is quoted: acute lymphoblastic leukemia (1 paper); acute myeloid leukemia (1); breast invasive carcinoma (1); cholangiocarcinoma (1); colon adenocarcinoma (1); diffuse large B-cell lymphoma (1); endometrial cancer (1); glioblastoma (1); head and neck squamous cell carcinoma (1); kidney chromophobe (1); lung adenocarcinoma (1); lymphoid neoplasm (1); mesothelioma (1); mitochondrial disease (1); ovarian mucinous tumors (1); pancreatic adenocarcinoma (1); prostate adenocarcinoma (1); rectum adenocarcinoma (1); sarcoma (1); skin cutaneous melanoma (1); small cell lung carcinoma (1); stomach adenocarcinoma (1); thyroid carcinoma (1); uterine corpus endometrial carcinoma (1).